ZNF709 (zinc finger protein 709)
Description:
May be involved in transcriptional regulation.
Synonyms: FLJ38281
Tractability: PROTAC: ubiquitination databases record sites on it.
Gene: Protein-coding gene on chromosome 19 (12,461,184 to 12,513,854, reverse strand). Ensembl gene ENSG00000242852.
Subcellular location: Nucleus
Subcellular location (Human Protein Atlas): Nucleoplasm
Pathways (Reactome):
Gene expression (Transcription): Generic Transcription Pathway
Gene Ontology:
Molecular function: DNA-binding transcription factor activity, RNA polymerase II-specific; RNA polymerase II transcription regulatory region sequence-specific DNA binding
Biological process: regulation of transcription by RNA polymerase II; regulation of DNA-templated transcription
Cellular component: nucleus
Genetic constraint (gnomAD): Loss-of-function variants: 15 observed, 11.02 expected, observed/expected ratio (o/e) 1.36, 90% interval 0.9 to 1.88. The upper end of that interval is the gene's LOEUF score, 1.88, which puts it in group 6 of 6, group 1 being the genes least tolerant of losing a copy. Missense variants: 589 observed, 781.71 expected, observed/expected ratio (o/e) 0.75, 90% interval 0.7 to 0.81. Synonymous variants: 194 observed, 233.64 expected, observed/expected ratio (o/e) 0.83, 90% interval 0.74 to 0.94.
Homologues: Orthologues: chimpanzee ZNF709 (100% identical), rabbit ZNF709 (92% identical), rat Znf709l (83% identical), dog ZNF791 (63% identical), guinea pig ZNF709 (46% identical). Paralogues in human: ZNF14 (61% identical), ZNF433 (59% identical), ZNF791 (57% identical), ZNF44 (55% identical), ZNF700 (55% identical), ZNF823 (54% identical), ZNF799 (53% identical), ZNF443 (53% identical), ZNF442 (51% identical), ZNF441 (51% identical), ZNF878 (50% identical), ZNF563 (41% identical), and 3 more.
Diseases named in the same sentence as ZNF709 in open-access papers:
ZNF709 is named in the same sentence as 6 diseases in open-access papers, as found by Europe PMC text mining. Sharing a sentence is not in itself a finding about the gene and the disease. The quoted sentences say what the papers report.
pancreatic cancer (2 papers, 2021 to 2024). "A total of 8 immune genes (ITGA7, RBM14, DENND4B, LQK1, ZNF709, COL7A1, SP1, NCBP2) were identified as independent prognostic factors of pancreatic cancer, which were used to construct a clinical predictive model." (PMID 33546693, 2021). "However, NCBP2, RBM14, LQK1, and ZNF709 have not been reported to be related to pancreatic cancer." (PMID 33546693, 2021).
breast carcinoma (1 paper, 2024). "The Human Protein Atlas reports strong expression of ZNF709 in cancers such as thyroid, colorectal, and breast cancer." (PMID 39118043, 2024).
leukemia (1 paper, 2020). A malignant (clonal) hematologic disorder, involving hematopoietic stem cells and characterized by the presence of primitive or atypical myeloid or lymphoid cells in the bone marrow and the blood. "Specifically, the differentially expressed gene RAS oncogene family like 6 (RABL6, also known as RBEL1 and C9orf86), CD93, and Zinc Finger Protein 709 (ZNF709) have been implicated in cancers and leukemia." (PMID 32134197, 2020).
cancer (4 papers, 2020 to 2025). A tumor composed of atypical neoplastic, often pleomorphic cells that invade other tissues. "However, 50 transcription factors displayed similar interactions with SWI/SNF in the two cancer types, such as several zinc-finger transcription factors (ZNF512, ZNF598, ZNF609, ZNF687, and ZNF709), CTCF, ELF2, and YBX1, indicating shared gene regulation networks." (PMID 40988026, 2025).
tumor (1 paper, 2024).
ZNF709 also shares sentences with these, for which no sentence is quoted: clear cell renal carcinoma (1 paper).